KDM4B (lysine demethylase 4B)
Diseases named in the same sentence as KDM4B in open-access papers (continued):
Sharing a sentence is not in itself a finding about the gene and the disease.
tumor (54 papers, 2011 to 2025). "The overexpression of KDM4B was associated with increased tumor size and enhanced risk of liver metastasis in a mouse xenograft model of renal clear cell carcinoma (RCCC)." (PMID 40940894, 2025). "In sum, we demonstrate that KDM4B acts as a co-activator of c-Myc, a widely oncogenic factor implicated in tumor development and progression." (PMID 34335964, 2021). "Collectively, these results demonstrate that the loss of KDM4B in CRC cells results in the suppression of tumor growth and the suppression can be partly rescued by constitutively active AKT." (PMID 31931846, 2020). "KDM4B is required for ERα dependent transcription, where loss of KDM4B decreases cell proliferation in vitro and tumor progression in vivo." (PMID 30759871, 2019). "Increased expression of LOX in EOC patient tumor samples associates with poor progression-free survival, linking a putative KDM4B target gene to disease progression." (PMID 27869162, 2017). "Loss of KDM4B significantly inhibited peritoneal seeding and tumor growth for both SKOV3ip.1 and OVCAR8 cells, as measured by bioluminescence." (PMID 27869162, 2017). "Our findings are consistent with previous publications demonstrating that loss of KDM4B decreases tumorigenic behavior, while extending the field into a tumor type that has previously received little attention from the histone demethylase field." (PMID 27869162, 2017). "Deregulation of cell apoptosis was shown to be the major cause of tumor growth, so we next investigated the role of KDM4B in CRC cell apoptosis." (PMID 27506941, 2016). "Moreover, an enhanced expression of PD‐L1 was detected in JIB‐04‐treated or KDM4B‐deficient tumour tissues." (PMID 38390756, 2024). "KDM4B overexpression is associated with tumor growth in gastric cancer." (PMID 30683841, 2019). "Under certain conditions, such as infection with nucleic acid from virus or dead tumor cells, KDM4B demethylates cGAS, untethering it from chromatin and allowing its translocation into the cytoplasm where it becomes activated." (PMID 40595456, 2025). "The inhibitor QC6352 binds KDM4B, suppresses its activity, delays tumor progression, and exhibits minimal toxicity." (PMID 40508013, 2025). "Future studies will incorporate functional assays using BTC-derived organoids and CRISPR-based editing to determine how KDM4B, KDM5C, and KDM6A mutations contribute to epigenetic dysregulation and tumor initiation." (PMID 41301905, 2025). "The present study further identifies KDM4B as a crucial demethylase that enhances cGAS activity by removing its methylation modification, thereby promoting anti-tumor immune responses." (PMID 40595456, 2025). "Collectively, these findings demonstrate that KDM4B facilitates anti-tumor immunity and enhances the efficacy of immunotherapy by demethylating and activating cGAS." (PMID 40595456, 2025). "Specific methyltransferases such as EZH2, EHMT1/2, and KMT1A, and demethylases including KDM3A/B and KDM4B, form oncogenic axes that sustain tumor growth and block myogenesis." (PMID 40508013, 2025). "In order to investigate the potential involvement of the PD‐1/PD‐L1 pathway in adaptive immune resistance after KDM4 inhibition, we measured PD‐L1 levels on tumour cells following JIB‐04 treatment or genetic deletion of KDM4B." (PMID 38390756, 2024). "In COAD and SKCM Gene Expression Omnibus (GEO) cohorts, tumour tissues exhibited higher expression of KDM4B." (PMID 38390756, 2024). "In human tumours, KDM4B expression was negatively correlated with clinical outcomes, type I interferon signatures, and responses to immunotherapy." (PMID 38390756, 2024). "We next assessed the correlation between KDM4B expression and the abundance of tumour‐infiltrating immunocytes in 30 human cancers." (PMID 38390756, 2024).
tumor (continued). "RNA-sequencing (RNA-seq) analysis of 566 samples (44 normal and 522 tumour) suggested that LEF1, KDM4A, and KDM4D were expressed at higher levels in tumour tissues than in normal tissues, whereas KDM4B was expressed at lower levels in tumour tissues." (PMID 37553362, 2023). "Immunohistochemical analysis of tumor tissues showed that MYC expression was downregulated after KDM4B knockdown, while FBXL3 and CRY2 expression was upregulated." (PMID 38093312, 2023). "Our study has uncovered a KDM4B-dependent epigenetic mechanism in the control of tumor progression, providing a rationale for utilizing KDM4B as a promising therapeutic target for the treatment of MYC-amplified GBM." (PMID 38093312, 2023). "Collectively, our findings indicate that KDM4B promotes tumor progression through the miR-181d-5p/SCFFBXL3+CRY2/MYC axis." (PMID 38093312, 2023). "KDM4A serves as a coactivator of E2F1 and KDM4B regulates AR signaling and turnover to promote tumor progression." (PMID 35534851, 2022). "Our findings were consistent with the finding that KDM4B downregulation in KDM4B-knockdown C4-2B cells impaired tumor growth in C4-2B xenografts." (PMID 35534851, 2022). "RMS cells resemble undifferentiated skeletal muscle cells and thus present an undifferentiated phenotype that has been attributed to the overexpression of epigenetic proteins in these tumours, in line with data we present here for KDM4B." (PMID 33917420, 2021). "In the current research, we identified a potent inhibitory function of miR-545 on OC cell and tumor growth through the suppression of PLK1 by direct binding or an indirect regulation by abrogating KDM4B-mediated PLK1 activation." (PMID 33588776, 2021). "KDM4B knockdown led to a significant impairment of tumor growth in C4-2B and CWR22Rv1 xenografts (p = 0.0159 and p = 0.0286, respectively)." (PMID 34335964, 2021). "qRT-PCR analysis further revealed that mitochondrial glutaminase 1 (GLS1), involved in tumor growth 44, and phosphoenolpyruvate carboxykinase (PCK2), which regulates tumor-initiating cells 45, were substantially downregulated by the depletion of KDM4B." (PMID 34335964, 2021). "In this study, we show that KDM4B knockdown effectively impairs the viability of AR-positive CRPC cells as well as the tumor growth in xenografts." (PMID 34335964, 2021). "Further investigation is needed to evaluate the metabolic dependence in the context of the KDM4B status, tumor genetic background, or the composition of the tumor microenvironment." (PMID 34335964, 2021). "These KDM4A−KDM4D proteins were reported to be involved in the pathogenesis of solid tumors, and we previously identified a tumor‐promoting role of KDM4B in estrogen receptor‐positive breast cancer." (PMID 34938963, 2021). "We further provide evidence that KDM4B and c-Myc work together to modulate energy metabolism in CRPC, and the inhibition of KDM4B decreases tumor growth via a metabolic switch." (PMID 34335964, 2021). "In support of this, we detected lower Ki-67 staining in KDM4B knockdown tumor tissues and stronger Ki-67 staining in simultaneous KDM4B knockdown and AKT constitutively activation tumor tissues by the immunohistochemistry analysis." (PMID 31931846, 2020). "But the inhibition of tumor growth by KDM4B knockdown was partially rescued when AKT was constitutively active in the meantime in vivo." (PMID 31931846, 2020). "We found that KDM4B knockdown significantly suppressed tumor growth, both in the tumor volume and weight." (PMID 31931846, 2020). "In the following sections, we will attempt to synthesize what is known regarding the context-dependent expression of KDM4B as a mediator of tumor progression in multiple cancer types." (PMID 30759871, 2019). "Given the central importance of epigenetic regulation in tumor progression, inhibitors of KDM4B and many other JmjC-KDMs are being actively developed for clinical application." (PMID 30759871, 2019).
tumor (continued). "The cross-talk between HIF-1α and ERα converges at KDM4B, which is important for cell cycle progression and tumor growth in ER positive breast cancer." (PMID 29342868, 2018). "Stable knockdown of KDM4B disrupted invasion and migration in vitro, consistent with diminished peritoneal tumor load in mouse xenografts." (PMID 27869162, 2017). "The in vivo role of KDM4B in EOC tumor progression was determined using intraperitoneal tumor xenografts." (PMID 27869162, 2017). "KDM4B was expressed in hypoxic regions of tumor epithelium as determined by pimonidazole and PAX8 staining (respectively)." (PMID 27869162, 2017). "Average intensity of CA-IX staining for triplicate tumor sections in the HGSA tumors (range 0–3) was positively correlated to the percentage of KDM4B-positive tumor nuclei." (PMID 27869162, 2017). "Expression of KDM4B in tumors is positively correlated with expression of the tumor hypoxia marker CA-IX, and is robustly induced in EOC cell lines exposed to hypoxia." (PMID 27869162, 2017). "Taken together, our data revealed that miR-615-5p functions as a tumor suppressor that is epigenetically silenced by downregulation of KDM4B in HCC." (PMID 27487123, 2017). "OVCAR8 cells expressing shRNA to KDM4B developed less ascites fluid compared with controls, consistent with the effect on tumor seeding and growth." (PMID 27869162, 2017). "We next assessed tumor growth of KDM4B-depleted cell lines using a mouse xenograft model based on subcutaneous injection." (PMID 27506941, 2016). "KDM4B mRNA levels were significantly higher in tumor samples than normal tissues (P = 0.0011), and KDM4B protein was also overexpressed in CRC specimens, as assessed by western blot." (PMID 27506941, 2016). "Demethylases (e.g., KDM3A/B, KDM4B) reverse these marks and promote tumor growth." (PMID 40508013, 2025). "Accordingly, shRNA-mediated KDM4B knockdown reduced xenograft tumor growth." (PMID 40940894, 2025). "Furthermore, we observed that deletion of KDM4B among all KDM4 family members yielded the greatest amount of Granzyme‐B in tumour tissues." (PMID 38390756, 2024). "In patients with these indicators, the CNV level of KDM4B is significantly increased, suggesting that abnormal expression of KDM4B may be related to tumor development." (PMID 38093312, 2023). "Genes PRKCZ (Protein Kinase C Zeta), FGR (Src family protein), KDM4B, MPO, COL11A1, FUT4 (Fucosyltransferase IV), and APEH (acylpeptide hydrolase) are directly associated with tumor aggressiveness, growth, and migration, and invasiveness, resulting in poor clinical outcome in cancer patients." (PMID 38086861, 2023). "Consistently, KDM4B and Ki-67 expressions were also inhibited in the tumor samples." (PMID 38093312, 2023). "Additionally, KDM4B co-activates c-Myc to directly promote c-Myc-mediated tumor metabolism contributing to CRPC progression." (PMID 35534851, 2022). "Further exploring the mechanism of KDM4B in normal and tumor tissues can we provide more reliable evidence for whether KDM4B will be used as a tumor marker or even as a gene target for tumor therapy." (PMID 35186950, 2021). "Our data demonstrated that KDM4B preferentially regulated distinct pathways in different oxygen microenvironments, suggesting that KDM4B may be an important factor for tumor hypoxia maintenance or promotion." (PMID 34766154, 2021). "In future, further studies on KDM4B in different tumors and tissues will provide more reliable evidence for whether KDM4B can be used as a tumor marker or even as a gene target for tumor therapy." (PMID 35186950, 2021). "KDM4B can promote tumor growth, apoptosis, metastasis and autophagy." (PMID 31931846, 2020). "Furthermore, we noted the existence of a significant correlation between tumor KDM4B expression levels and pathologic T stage, as well as clinical stage, who underwent pre-therapy surgery." (PMID 31931846, 2020).
tumor (continued). "The study of a co-regulatory mechanism between KDM3A and KDM4B in hypoxic signalling may therefore also be beneficial for the development of novel therapeutic strategies to abrogate hypoxia driven tumours." (PMID 31390833, 2019). "Although specifically restricting KDM4B inhibition to a tumor remains challenging, identifying conditions where KDM4B is inhibited by aberrant metabolite accumulation could more effectively direct the application of PARPis and other chemotherapeutics." (PMID 30759871, 2019). "Thus, miR-615-5p, who is downregulated by KDM4B-mediated hypermethylation in its promoter, functions as a tumor suppressor by inhibiting RAB24 expression in HCC." (PMID 27487123, 2017). "Thus, KDM4B represents a novel link between the hypoxic tumor microenvironment and EOC, mobilizing mechanisms that facilitate the establishment of peritoneal tumors." (PMID 27869162, 2017). "Our studies, like previous reports, imply that disrupting KDM4B function with a demethylase inhibitor may attenuate tumor growth." (PMID 27869162, 2017). "Combinatorial targeting of genes regulated by KDM4B may lead to improved methods to suppress peritoneal engraftment of EOC tumor cells, ultimately improving the prognosis of patients with elevated levels of KDM4B." (PMID 27869162, 2017). "Stable knockdown of KDM4B significantly repressed tumor growth compared with shControl cells." (PMID 27506941, 2016). "Furthermore, higher levels of KDM4B correlated with advanced tumor grade and depth of myometrial invasion in clinical EC specimens (*P < 0.05)." (PMID 26397136, 2015). "GBM cell lines and xenograft tumor samples were subjected to quantitative PCR (qPCR), Western blot, immunohistochemical staining (IHC), as well as ubiquitination, immunoprecipitation (IP), and chromatin immunoprecipitation (ChIP) assays to investigate the role of KDM4B in the progression of GBM." (PMID 38093312, 2023). "Furthermore, ectopic expression of KDM4B enhances tumor growth in vivo." (PMID 35186950, 2021). "Interestingly, compared with our study, although different techniques and samples types (tumors and circulating leukocytes) were used, some genes described by Ferraresso and colleagues in tumor also presented aberrant methylation in canine leukocyte DNA (KDM4B, HOX, WNT and FGFR2)." (PMID 30908498, 2019). "Importantly, KDM4B knockdown inhibited tumor growth and increased the level of apoptosis in mouse xenograft tumors, indicating that KDM4B may be a potential target for therapeutic intervention." (PMID 27506941, 2016). "Importantly, KDM4B knockout animals are phenotypically normal, indicating that the enzyme is not a general regulator of cellular proliferation and aberrant expression in BCa is acquired on cellular transformation, suggesting targeting KDM4B is potentially tumour specific." (PMID 23723241, 2013). "Notably, Kdm4b knockout accelerated tumor progression compared to the control group, whereas Kdm4b deficiency failed to further increase the effect of Cgas knockout on tumor growth, suggesting that KDM4B regulates tumor progression in a cGAS-dependent manner." (PMID 40595456, 2025). "UCHL1’s interaction with KDM4B is crucial for CCRCC malignancy and targeting UCHL1 has been shown to suppress tumor growth and enhance sensitivity to bevacizumab." (PMID 39199615, 2024). "In TCGA pan‐cancer database, tumour tissues generally exhibited higher expression levels of KDM4A, KDM4B and KDM4D compared to normal tissues." (PMID 38390756, 2024). "Further investigation of the cistromic interplay between KDM4B, GATA3 and AR in the breast is required to definitively identify how KDM4B contributes to AR-mediated luminal programs and tumor suppression in the breast." (PMID 38317241, 2024). "miR-491-5p directly targets JMJD2B/KDM4B, a histone demethylase with oncogenic features, suggesting a possible downstream epigenetic-mediated tumor suppressor effect." (PMID 37369946, 2023).
tumor (continued). "Taken together, these data provide direct evidence that KDM4B epigenetically enhances MYC stability and shed new light on its oncogenic activity in tumor development." (PMID 38093312, 2023). "JIB-04, the most advanced preclinical KDM4 inhibitor, inhibits growth and lowers tumor burden in non-small cell lung cancer and breast cancer, both in vitro and animals, and targets KDM4A, KDM4B, and KDM4E." (PMID 37218871, 2023). "Among the genes negatively regulated by KDM4B, STARD7, CPA4, FKBP14, and RNF6 have been shown to regulate cell proliferation and/or metastasis, whereas DYRK2 is a known tumor suppressor." (PMID 34766154, 2021). "To clarify the regulatory effect of miR-15a on the KDM4B/HOXC4/PD-L1 axis, we further examined the protein expression of KDM4B, HOXC4, and PD-L1 in tumor tissues using western blot." (PMID 33732698, 2021). "Nonetheless, they observed elevated expression of KDM4B, XBP1, AR, MYB, and SPDEF in early neoplasias compared to normal which were also elevated in our profile." (PMID 31248446, 2019). "Combined, these data suggest KDM4B regulates distinct functions in different oxygen tensions, providing multiple avenues to affect EOC tumor growth." (PMID 27869162, 2017). "Currently we cannot exclude the other possibility that KDM4B regulates anti-tumor immunity through other mechanisms." (PMID 40595456, 2025). "KDM4B stabilizes MYC expression through epigenetic regulation, driving tumor progression." (PMID 40565099, 2025). "The small molecule KDM4B inhibitor B3 sensitized C-R PC cells and C-R PC xenografts to enzalutamide (nonsteroidal AR inhibitor), and synergistically blocked tumor growth in combination with rapamycin." (PMID 40940894, 2025). "Indeed, we noted a robust correlation in the expression of KDM4A, KDM4B, KDM4C and KDM4D across all tumour samples in the TCGA pan‐cancer database." (PMID 38390756, 2024). "Our comparative transcriptomic analysis has identified a bunch of new Echinomycin-regulated, Myc- and HIF1α-related genes contributed to KSHV pathogenesis, including KDM4B and Tau, which are required for the survival of KSHV + tumor cells with functional validation." (PMID 37143124, 2023). "Forty out of 87 showed positive KDM4B staining in tumor tissue nuclei, but no signal in normal tumor-adjacent regions." (PMID 30683841, 2019). "In line with reports that the estrogen receptor (ER) regulates KDM4B expression, we observed upregulation of KDM4B in ER+ but not in ER- or TN tumors in agreement with KDM4B's oncogenic activity in other tumor types." (PMID 27863398, 2016). "Instead, our data demonstrates that KDM4B is a key regulator of ER gene transcription and FOXA1 expression that together control the estrogen-dependent phenotype of a high proportion of BCa cell lines and primary tumours." (PMID 23723241, 2013). "Additionally, ATAC peak profiles for target genes in patient recurrent tumor samples, showed proximal gene linkages in clusters mediating the progenitor_photoreceptor signature and cycling progenitors for regulators such as NFE2L2, HLX, HSPH1, and KDM4B." (PMID 39711559, 2024). "After confirming the mechanism that KDM4B promotes the expression of GLUT1 via the AKT signaling pathway in colorectal cells, we investigated whether AKT could rescue the KDM4B depress-induced suppression of tumor growth in mouse xenograft models." (PMID 31931846, 2020). "Our findings indicate that it is primarily tumour cells, not immune cells, contribute to the enhanced production of IFN‐β after JIB‐04 treatment or KDM4B deletion." (PMID 38390756, 2024). "Histone demethylase 4B (KDM4B) is abnormally expressed in GBM, but the molecular mechanisms by which KDM4B affects the malignant tumor progression are not well defined." (PMID 38093312, 2023).